CD44 (CD44 molecule (IN blood group))
Diseases named in the same sentence as CD44 in open-access papers (continued):
Sharing a sentence is not in itself a finding about the gene and the disease.
neurodegenerative disease (9 papers, 2015 to 2025). A disorder of the central nervous system characterized by gradual and progressive loss of neural tissue and neurologic function. "CD44, a receptor for hyaluronic acid (HA), a key component of the brain’s extracellular matrix, is thought to play important roles in axon guidance during neuronal development, and its upregulation has been associated to astrogliosis and neurodegenerative diseases." (PMID 30501627, 2018). "Also, over expression of CD44 in tissues of the central nervous system may confer on them susceptibility to apoptotic killing leading to neurodegenerative diseases." (PMID 26624007, 2015). "This literature demonstrates the abundance of both C1q and CD44 in the disease microenvironment and highlights the potential for C1q-CD44 interactions to modulate DAM state via a conserved mechanism across neurodegenerative disease." (PMID 41282250, 2025). "Cross-Disease Insights: Lessons from GPNMB’s role in neurodegenerative diseases, such as its neuroprotective interaction with CD44, might inspire therapies for brain metastases." (PMID 41180454, 2025). "Additionally, the presence of CD44 on other cell types, including dopamine neurons and microglia, suggests that GPNMB may represent a novel multi-target therapeutic approach to treat neurodegenerative diseases, including PD." (PMID 29519253, 2018).
inflammation (8 papers, 2013 to 2024). Aberrant reaction of the microcirculation characterized by movement of fluid and leukocytes from the blood into extravascular tissues. "To determine the effect of inhibiting CD44-ICD on the release of inflammatory mediators in LPS-induced hepatic inflammation in mice and Chang cells, we assessed the level of hepatic IL-1β, NO, and INOS in mice and the level of IL-1β in Chang cells." (PMID 39201593, 2024). "The results indicated that both treatments significantly reduced the number of CD4+CD44+ T cells, most of which were memory T cells, in addition to reducing lung inflammation and lower levels of Th2 cytokines, such as IL-4, IL-5, and IL-13." (PMID 39060348, 2024). "Previous studies report that TSG-6, via binding to CD44, induces a phenotypic shift in macrophages from proinflammatory M1 to anti-inflammatory M2 type that protects the mice against lung inflammation and injury induced by endotoxin lipopolysaccharide (LPS)." (PMID 29941022, 2018). "CD44 is a ubiquitously expressed cell-surface transmembrane receptor with multiple functions in inflammatory processes, including sterile renal inflammation." (PMID 24376813, 2013). "In a mouse model of allergen-induced airway inflammation, administration of exogenous Gal-9 inhibited airway inflammation by binding to CD44 and preventing CD44-hyaluronic acid interaction, an event that is essential for leukocyte adhesion and migration to the lung." (PMID 28620605, 2017). "Higher levels of CD44 in obese PMN might be in line with previously published data showing that HA-CD44 interaction is the main mechanism for leukocyte trafficking from the bloodstream into inflamed tissues and PMN recruitment within the hepatic microvasculature in systemic inflammation." (PMID 35896710, 2022).
renal disease (7 papers, 2021 to 2025). "While previous studies have implicated CD44 and RHAMM in renal disease and fibrosis, our work for the first time provides an integrated analysis of both receptors in the context of ORKP." (PMID 41301516, 2025). "As a supplement, our study revealed that HA can activate the highly profibrotic factor TGFβ through its dynamic receptor CD44, highlighting the role of HA/CD44 in activating TGFβ signaling, which is frequently observed to drive fibrosis in AS renal disease." (PMID 40075271, 2025). "CD44+ levels correlate with proteinuria, complement components in urine, and fibrosis severity, highlighting its role in kidney disease progression." (PMID 40809316, 2025). "In contrast to the many studies on CD44 and kidney diseases, there are few studies on RHAMM, limited to renal cell carcinomas." (PMID 41301516, 2025). "As an upstream activator, CD44 might be a more effective and specific therapeutic target than TGFβ itself for treating AS-related renal disease." (PMID 40075271, 2025). "Therefore, targeting CD44 and its pathways may be a promising therapeutic strategy to hinder fibrosis progression and improve the treatment of renal disease." (PMID 40075271, 2025). "Upregulation of CD44 expression in glomeruli and TEC is shown in case of inflammatory and autoimmune driven renal diseases." (PMID 37751458, 2023). "Furthermore, we analysed CD44 and RHAMM gene expression in patients with more advanced kidney diseases." (PMID 41301516, 2025). "CD44 may directly regulate biological processes such as monocyte aggregation and ECM-receptor interaction, and regulate renal water absorption, signaling and kidney disease/fibrosis through its interaction with HA, HAS2, hyaluronidase, TGF-β1 and FN." (PMID 39411720, 2024).
benign tumors (6 papers, 2007 to 2025). "This study aims to analyze differences in immunostaining intensity for CD44, CD133, and VDR among groups of benign tumors, low-grade atypical proliferative tumors, and five distinct malignant phenotypes (HGSC and non-HGSC)." (PMID 40332380, 2025).
head and neck tumors (4 papers, 2023 to 2024). "The surface receptor of hyaluronic acid and matrix metalloproteinases CD44 is involved in the processes of cell migration; a high level of CD44 expression in head and neck tumors is associated with the risk of metastasis and poor prognosis." (PMID 38540309, 2024).
immune disease (4 papers, 2019 to 2025). "In conjunction with the results of this study, it can be speculated that CD44 may be associated with immune dysfunction in IBS-D." (PMID 37007011, 2023).
neurological disorders (4 papers, 2020 to 2025). "Elucidating the cell-type-specific roles and regulation of CD44 variants may offer novel therapeutic strategies for diverse neurological disorders." (PMID 40943148, 2025). "A different arrangement of CD44 isoforms is associated with neurologic diseases, such as AD." (PMID 40943148, 2025). "By analogy with evidence reporting the glial expression of CD44 in a variety of neurologic diseases, the neuronal expression of CD44 was also observed in pathological conditions." (PMID 40943148, 2025). "TBI-induced protein upregulation (MUG-1, PZP, GFAP, TJP, STAT-1, and CD44) across hippocampal sub-regions indicates shared molecular responses and links to neurological disorders." (PMID 38735925, 2024). "CD44 plays a vital role in different events involved in the inflammatory process and in several neurological disorders." (PMID 33329306, 2020). "Furthermore, EVPs in the CSF with CD40 or CD44 present on their surface may potentially play functional roles in the immunopathogenesis of neurological diseases of viral etiology." (PMID 37622115, 2023). "In conclusion, understanding the intricate mechanisms by which CD44 mediates cell–cell and cell-ECM interactions, and how its signaling pathways are modulated in different neural cell types, offers promising avenues for therapeutic interventions targeting a wide range of neurological disorders." (PMID 40943148, 2025).
colon polyp (3 papers, 2017 to 2023). "The inhibition or degradation of ß-catenin induced the downregulation of its target gene CD44, ultimately influencing intestinal diseases through the Hippo pathway." (PMID 38130953, 2023). "Alternative splicing profile of CD44 in colon polyps differed substantially from alternative splicing profile of CD44 in adjacent healthy mucosa." (PMID 34257584, 2021). "Mouse anti-total CD44 IgG proved that CD44s is strongly downregulated also at the protein level in colon polyps." (PMID 34257584, 2021). "The localization of CD44v8-10 was the same as demonstrated with anti-total CD44, i.e., in the epithelial lining of the colon polyps." (PMID 34257584, 2021). "Our previous research on CD44 receptor lead us to analyse alternative splicing profile (ASP) of CD44 gene in colon polyps." (PMID 34257584, 2021). "We studied and compared alternative splicing profile of CD44 gene in colon polyps and adjoined healthy colon mucosa." (PMID 34257584, 2021). "Our results show that aberrant alternative splicing of CD44 in colon polyps might affect affinity of colonocytes to HA, the main component of extracellular matrix." (PMID 34257584, 2021). "High levels of the intestinal stem-cell marker MSI1 have been observed in CD44+ colon polyp cells." (PMID 29110645, 2017). "Crumbs, CD44, and MOB can affect intestinal diseases by interacting with the Hippo pathway." (PMID 38130953, 2023). "To shed more light on the mechanisms running in the background of our observation, i.e., overexpression of CD44v8-10 in colon polyps, we tested expression levels of RNA binding proteins ESRP-1 and ESRP-2 that are known to control ASP of CD44 in prostate epithelial cells." (PMID 34257584, 2021).
hematological cancers (3 papers, 2017 to 2020). "In hematological cancers, CD44 expression is functionally associated with chemotherapy resistance." (PMID 32849491, 2020). "LACHA-DOX has appeared as a highly appealing platform for targeted treatment of CD44 positive hematological cancers." (PMID 28958164, 2017). "It thus appears that HA could also be employed to direct nanomedicines to CD44 overexpressed hematological tumor cells for treating hematological malignancy." (PMID 28958164, 2017). "CD44 may control bone metastasis in hematopoietic cancers and solid tumors." (PMID 31579438, 2019).
blood cancer (2 papers, 2022 to 2023). "The CD20/CD44 dual-targeting outer layer offered precise binding to blood cancer cells, followed by receptor-mediated endocytosis of the LbL NPs." (PMID 36678782, 2023). "For example, CD20/CD44 dual targeted siRNA delivery using layer-by-layer NPs (LbL NPs, PLGA/PLA/siRNA/PLA; PLGA, poly-(D,L-lactide-co-glycolide); PLA, poly-l-arginine) with BCL-2 siRNA in B cell lymphoma and leukemia cells downregulated BCL-2, induced apoptosis, and reduced the blood cancer cells." (PMID 36678782, 2023). "Thus through CD44-mediated interactions between HSPCs and the BM microenvironment, CD44 can directly contribute to the regulation of HSC homing, engraftment, quiescence and prevention of apoptosis, and it can also be involved in the development of hematological neoplasms." (PMID 34838648, 2022).
cardiovascular disease (2 papers, 2021 to 2025). "In SGA infants, elevated CD44 expression in SGA-HUVECs may indicate an early onset of vascular aging in endothelial cells, potentially predisposing individuals to cardiovascular diseases over the long term." (PMID 40260916, 2025).
cardiac disease (1 paper, 2024). "Minor differences were observed in levels of CD8, CD49e, and CD11c after treatment with hypoglycemic agents, and in levels of CD62P, CD42a, CD44, and CD31, after treatment with anticoagulants, in patients with organ damage and/or cardiac disease." (PMID 39702460, 2024).
epithelial neoplasm (1 paper, 2012). A benign or malignant neoplasm that arises from and is composed of epithelial cells. "Altered levels of CD44 have been seen in many epithelial neoplasms and expression of CD44 has been shown to carry prognostic implications." (PMID 22966907, 2012).
gynecological tumors (1 paper, 2020). "Other gynecological tumors on average had a higher expression level of CD44 than SCCOHT primary tumors." (PMID 33355532, 2020).
infectious disease (1 paper, 2022). A disorder directly resulting from the presence and activity of a microbial, viral, or parasitic agent in humans. "CTSD (cathepsin D), CD44 (CD44 antigen), and COL1A2 (collagen alpha-2) were associated with the pathways of “infectious disease: viral” and “immune system”." (PMID 36704102, 2022).
CD44 also shares sentences with these, for which no sentence is quoted: multiple myeloma (13 papers); metabolic disorders (7); idiopathic pulmonary fibrosis (6); chronic atrophic gastritis (5); osteoporosis (5); Hodgkins lymphoma (4); leukoplakia (4); oropharyngeal squamous cell carcinoma (4); Allergy (3); bone metastasis (3); colon (3); Epithelial Ovarian Tumors (3); germ cell tumor (3); interstitial lung disease (3); intrahepatic cholangiocarcinoma (3); lung carcinoid tumor (3); malignant peripheral nerve sheath tumor (3); papillary carcinoma (3); pharyngeal cancer (3); polycystic ovary syndrome (3); retinoblastoma (3); adrenocortical carcinoma (2); autism (2); benign breast disease (2); benign papilloma (2); cancers of the oral cavity (2); cardiac arrhythmias (2); chronic prostatitis (2); coronary artery stenosis (2); dermatitis (2).
A further 191 diseases each share a sentence with CD44 in 2 papers or fewer.